GDF15 (growth differentiation factor 15)
Diseases named in the same sentence as GDF15 in open-access papers (continued):
Sharing a sentence is not in itself a finding about the gene and the disease.
IgA nephropathy (5 papers, 2018 to 2025). "Research on IgA nephropathy and idiopathic membranous nephropathy has shown that increased serum levels of GDF-15 are closely linked to impaired kidney function and disease progression." (PMID 40722837, 2025). "Our previous work in patients with IgA nephropathy showed that serum GDF-15 is significantly associated with adverse renal function and histologic findings." (PMID 29682097, 2018). "Previous studies demonstrated that high circulating GDF-15 levels had a significant correlation with a faster decline of renal function in patients with type 1 DM, IgA nephropathy, and CKD stages 1–4." (PMID 29682097, 2018).
infarction (5 papers, 2016 to 2025). A localised pathological necrosis of tissue resulting from obstruction of the blood supply usually by a thrombus, an embolus, or vascular torsion. "Analysis of a previously published dataset (GSE59867) revealed significantly elevated GDF15 expression in peripheral blood of MI patients, suggesting a critical role in mediating post-infarction cardiac remodeling." (PMID 41023695, 2025). "Consequently, higher preformation and release of GDF-15 during an ischemic period of infarction can be directly related to inflammatory-cell accumulation participating in the microcirculation injury." (PMID 36615045, 2022). "For both infarction groups, we found significantly higher levels of interleukin-2 receptor subunit alpha (IL2-RA) and growth/differentiation factor-15 (GDF-15)." (PMID 33396480, 2020).
interstitial lung disease (5 papers, 2018 to 2025). A diverse group of lung diseases that affect the lung parenchyma. "GDF15 was associated with fibrotic interstitial lung diseases so it may be indicate fibrotic remodeling of the lung impairment." (PMID 40247373, 2025). "Moreover,a recent study found patients with scleroderma-associated interstitial lung disease have increased expression of GDF15 as well as shorter TL in lung tissue.However,another study including 169 healthy volunteers did not found associations between GDF15 with telomerase." (PMID 39904253, 2025). "Candidate biomarkers CXCL9, GDF15, and vWF have previously been shown to correlate with global JDM activity, and WFDC2 and TNFSF13 have been associated with interstitial lung disease in DM." (PMID 39529136, 2024). "First, we analyzed the expression of CST3 and GDF15 in lung tissues of patients with and without interstitial lung disease (ILD)." (PMID 29724997, 2018).
Miscarriage (5 papers, 2014 to 2024). A pregnancy that ends at a stage in which the fetus is incapable of surviving on its own, defined as the spontaneous loss of a fetus before the 22th week of pregnancy. "Given the high rates of early clinical and pre-clinical miscarriage found in human pregnancies, selective advantages of GDF15 production in this regard should be especially strong." (PMID 38711789, 2024). "In the placenta GDF-15 is physiologically highly expressed and low expression of GDF-15 is associated with miscarriages." (PMID 30645608, 2019). "I describe three main lines of evidence relevant to the hypothesis that GDF15 production is typically adaptive for the fetus, in the context of enhanced placental invasion, reduced rates of miscarriage and preterm birth and higher birth weight." (PMID 38711789, 2024). "Early studies have shown that low serum GDF-15 levels correlate with miscarriages, indicating that it might be able to suppress inflammation in early pregnancy." (PMID 24484525, 2014).
muscle atrophy (5 papers, 2018 to 2025). The loss of muscle tissue due to inactivity or disease. "On the contrary, knockdown of GDF-15 in cachexic C26 cells could significantly decrease the potency of both C26 conditioned medium and C26 exosomes in inducing muscle atrophy." (PMID 35379793, 2022).
myeloproliferative neoplasm (5 papers, 2015 to 2023). A clonal hematopoietic stem cell disorder, characterized by proliferation in the bone marrow of one or more of the myeloid (i.e., granulocytic, erythroid, megakaryocytic, and mast cell) lineages. "There was a significant interaction between solid and haematological malignancies with loss of association of GDF‐15 with outcome in myelodysplastic and myeloproliferative disease." (PMID 31463975, 2019). "GDF15 levels were higher in the myeloproliferative neoplasm (MPN) group (P = 0.002)." (PMID 30761871, 2019).
open-angle glaucoma (5 papers, 2021 to 2024). Chronic outflow obstruction of the eye's drainage canals that can lead to increased internal eye pressure and optic nerve damage. "This is in line with a recently published study, in which plasma levels of GDF-15 assessed in patients with open angle glaucoma were found to be strongly confounded by age and vascular diseases." (PMID 34572118, 2021).
osteoporosis (5 papers, 2022 to 2026). A condition of reduced bone mass, with decreased cortical thickness and a decrease in the number and size of the trabeculae of cancellous bone (but normal chemical composition), resulting in increased fracture incidence. "Additionally, elevated levels of GDF15 were linked to a detrimental impact on osteoporosis and death, indicating a beneficial feedback loop involving the metformin target GDF15 in muscle composition, skeletal muscle metabolism." (PMID 40119457, 2025). "We conclude that GDF15 may influence glucometabolic status, body composition and bone parameters which may affect cardiovascular risk and osteoporosis between races." (PMID 39668628, 2024). "This study primarily attempted to reveal the role of GDF-15 in bone and muscle metabolism in patients with osteoporosis." (PMID 36325442, 2022). "This study aims to clarify the potential role of growth differentiation factor-15 (GDF-15) as a myokine in bone metabolism and muscle function in females with osteoporosis." (PMID 36325442, 2022). "Furthermore, GDF15 was found to be negatively correlated with osteoporosis (OR = 0.455, 95%CI 0.283–0.730, p = 0.001), as well as death (HR = 0.990, 95% CI 0.986–0.995, p < 0.001)." (PMID 40119457, 2025). "Finally, GDF15 levels were positively correlated with osteoporosis in patients with thalassemia suggesting its potential influence in bone health as well." (PMID 39668628, 2024). "Therefore, the aim of the current study was to clarify the potential role of GDF-15 as a myokine in bone metabolism and muscle function in patients with osteoporosis." (PMID 36325442, 2022). "Hence, the aim of this study was to investigate the potential role of GDF-15 as a myokine in bone metabolism and muscle function in patients with osteoporosis." (PMID 36325442, 2022). "However, the effect of GDF-15 as a myokine on bone metabolism and sarco-osteoporosis in humans is not clear." (PMID 36325442, 2022).
paroxysmal AF (5 papers, 2017 to 2022). "In addition, circulating GDF-15 level was reckoned independently associated with paroxysmal AF after multivariable analyses." (PMID 33115406, 2020). "According to multivariable analyses, GDF-15 was independently associated with paroxysmal AF." (PMID 28785588, 2017). "In the previous study, the significantly higher serum levels of GDF-15 were found in patients with paroxysmal AF than those of controls (1473.14 ± 628.52 vs. 1233.592 ± 262.76 pg/ml, p < 0.05)." (PMID 33115406, 2020). "Baseline serum GDF-15 level in the persistent AF group was significantly higher than the paroxysmal AF group [1140(854~1701)ng/L vs. 1062(651~1374)ng/L, P = 0.039]." (PMID 32904560, 2020). "Patients with paroxysmal AF had a significantly higher serum level of GDF-15 compared to the control group." (PMID 28785588, 2017). "Moreover, our study found that the expression of GDF-15 in serum elevated in the persistent AF group compared with the paroxysmal AF group, also elevated in the recurrence group compared with the non-recurrence group, and decreased after RFCA." (PMID 32904560, 2020). "Secondly, for paroxysmal AF patients, the rhythm may be different at the time of blood collection, which could make an effect on GDF-15 expression." (PMID 32904560, 2020). "To summarize, galectin-3, MMP-9, GDF-15, and PIIINP are promising markers in the prediction of paroxysmal AF, while TGF-β1 shows a lower potential." (PMID 28785588, 2017). "AF patients have also been shown to display higher values of GDF-15, a protein member of the transforming growth factor beta superfamily, than non-AF patients, GDF-15 being independently associated with paroxysmal AF." (PMID 29587379, 2018).
renal fibrosis (5 papers, 2020 to 2026). A final common manifestation of a wide variety of chronic kidney diseases characterized by glomerulosclerosis and tubulointerstitial fibrosis. "GDF15 deficiency exacerbates renal fibrosis, whereas GDF15 overexpression attenuates fibrotic changes, suggesting a protective role for GDF15 against renal fibrosis." (PMID 38892145, 2024). "Importantly, our findings indicate that renal fibrosis exacerbation is associated with decreased expression of GDF15." (PMID 41474228, 2026). "Mechanistically, GDF15 ameliorates renal fibrosis by enhancing autophagy through the PI3K/Akt/mTOR pathway." (PMID 41474228, 2026). "Collectively, these observations suggest that GDF15 holds promise as a potential therapeutic target for mitigating renal fibrosis." (PMID 41474228, 2026). "We further substantiated this finding by silencing or overexpressing GDF15 in vitro and in vivo models of renal fibrosis." (PMID 41474228, 2026). "Mechanistically, GDF15 inhibits renal fibrosis by suppressing the transforming growth factor-beta 1 (TGF-β1)-mediated epithelial-mesenchymal transition (EMT) and fibroblast activation." (PMID 38892145, 2024). "We therefore cannot postulate urinary GDF-15 as a biomarker of either renal function or renal fibrosis." (PMID 32089755, 2020). "Thus, the present study aimed to investigate the potential role of GDF15 in renal fibrosis in patients with CKD and a mouse model of unilateral ureteral obstruction (UUO), while also delving into the mechanisms and therapeutic implications of GDF15." (PMID 41474228, 2026). "Due to the correlation between GDF-15 and renal function in the present study and strong associations between circulating GDF-15 and fibrosis in other organ systems, we consider the relationship between GDF-15 (urinary and circulating) and renal fibrosis to be worth further exploration." (PMID 32089755, 2020). "Moreover, our findings demonstrate that inhibiting GDF15 expression exacerbates ECM accumulation, while upregulating GDF15 diminishes renal fibrosis." (PMID 41474228, 2026).
systemic lupus erythematosus (5 papers, 2022 to 2025). An autoimmune multi-organ disease typically associated with vasculopathy and autoantibody production. "This study discussed GDF-15 serum levels and gene polymorphisms in SLE patients and lupus mouse model further demonstrated the role of GDF-15 in lupus development." (PMID 35911685, 2022). "However, how the mutations contribute to lupus pathogenesis needs to be discussed in the future, and discussing the potential of GDF-15 gene polymorphisms as genetic marker for SLE is necessary to be confirmed with multi-center, larger sample sizes." (PMID 35911685, 2022). "Therefore, we cannot conclude whether GDF-15 gene polymorphisms affect GDF-15 expression, which may participate in lupus progression." (PMID 35911685, 2022). "In a related study, Xu WD and colleagues reported that individuals diagnosed with systemic lupus erythematosus exhibited elevated serum GDF-15 concentrations compared to healthy subjects." (PMID 40722837, 2025). "Consistently, our study showed that the proportion of CD11c+ and CD8+ cells was decreased when GDF-15 was injected into lupus mice." (PMID 35911685, 2022). "In our present study, based on mice models, we found that GDF-15 alleviated lupus by reducing renal damage, reversing CD8+, CD19+, and TH2 cells dysregulation, inhibiting production of IL-1β, IL-2, IL-4, IL-21, IL-22, ANA, and total IgG." (PMID 35911685, 2022). "Our findings showed that IL-1β expression was higher in pristane-induced lupus mice, and expression of IL-1β was significantly inhibited by GDF-15 treatment." (PMID 35911685, 2022). "GDF-15 treatment significantly reduced levels of IL-1β, IL-2, IL-4, IL-21, and IL-22, by which treatment of lupus mice with 100 μg/kg GDF-15 had the most efficiency." (PMID 35911685, 2022). "Addition of recombinant GDF-15 into pristane-induced lupus mice evaluated histological and serological changes." (PMID 35911685, 2022). "Percentages of CD8+, CD11b+, CD19+, CD11C+ cells, TH2 cells, and pro-inflammatory cytokines (IL-1β, IL-2, IL-4, IL-21, and IL-22) were reduced after GDF-15 treatment in lupus mice." (PMID 35911685, 2022). "Clarifying the divergence between disease suppressing effects of GDF-15 in the mouse model and its positive correlation with SLEDAI in SLE patients is useful to understand role of GDF-15 in lupus." (PMID 35911685, 2022). "Second, we conducted a lupus mouse model to confirm the functional role of GDF-15 in lupus development." (PMID 35911685, 2022). "Addition of GDF-15 treatment significantly reduced ANA and total IgG levels in lupus mice, by which 100 μg/kg GDF-15 injection had the best efficacy." (PMID 35911685, 2022). "Scores of HE, Masson, and fluorescence intensity indicated that lupus mice injected with 100 μg/kg GDF-15 showed the highest therapeutic efficacy." (PMID 35911685, 2022). "For instance, which signaling or what mechanism is involved in GDF-15 negatively regulates lupus development." (PMID 35911685, 2022). "Moreover, administering GDF-15 to lupus-prone mice led to a decrease in several proinflammatory cytokines, including IL-1β, IL-18, and IL-22, highlighting its role in modulating the immune response." (PMID 40722837, 2025). "Thus, GDF-15 is required for maintaining homeostasis, which relieves lupus progression by regulating innate and adaptive immune responses." (PMID 35911685, 2022). "However, mechanisms that GDF-15 regulates the indexes to involve in lupus pathogenesis need further elucidation." (PMID 35911685, 2022). "Lupus mouse model further demonstrated the role of GDF-15 in lupus development." (PMID 35911685, 2022). "In conclusion, GDF-15 was related to lupus pathogenesis and inhibited lupus development." (PMID 35911685, 2022). "Moreover, increased expression of IL-2, IL-21, and IL-22 in lupus mice was downregulated by GDF-15 treatment." (PMID 35911685, 2022). "The pristane-induced lupus mice treated with GDF-15 had alleviated disease activity." (PMID 35911685, 2022).
systemic lupus erythematosus (continued). "Accumulating evidence from in vivo functional studies has suggested that GDF15 may be an important regulator of inflammation in the body; for example, GDF15 has been shown to have inhibitory effects on experimental systemic lupus erythematosus and glomerulonephritis." (PMID 38655264, 2024). "However, renal damage and IgG deposition were alleviated when lupus mice were treated with GDF-15." (PMID 35911685, 2022). "Moreover, percentages of CD19+, CD3+, and TH2 cells were reduced in lupus mice by GDF-15 treatment." (PMID 35911685, 2022). "After GDF-15 treatment (100 μg/kg), CD8+, CD11b+, CD19+, CD11C+, and TH2 cells were significantly decreased compared to those in pristane-induced lupus mice, and this was the most efficient compared to what other does." (PMID 35911685, 2022). "GDF-15 treatment did not significantly reduce the weight of the liver, spleen, and kidneys in lupus mice." (PMID 35911685, 2022). "Lupus mice showed splenomegaly, severe histological scores, and high levels of autoantibodies [antinuclear antibodies (ANA) and total immunoglobulin G (IgG)], whereas administration of GDF-15 into lupus mice reduced the histological changes." (PMID 35911685, 2022). "In the present study, GDF-15 treatment reversed the increased percentage of CD11b+ cells in lupus mice, suggesting that there may be a negative feedback mechanism that high expression of GDF-15 could restrain CD11b+ cells proliferation." (PMID 35911685, 2022). "However, GDF-15 treatment significantly reduced levels of ANA and total IgG in lupus mice." (PMID 35911685, 2022).
Ureteral obstruction (5 papers, 2020 to 2026). Obstruction of the flow of urine through the ureter. "In this study, we investigated the role and mechanisms of GDF15 in TIF using a mouse model of unilateral ureteral obstruction (UUO) and human tubular epithelial cells (HK2) stimulated by transforming growth factor‐β1 (TGF‐β1)." (PMID 41474228, 2026). "Moreover, an anti-fibrotic effect has been attributed to GDF15 by the blockage of the TGF-β receptor and the N-Myc signalling pathways in a ureteral obstruction model after GDF15 administration." (PMID 35883655, 2022). "Serum GDF-15 levels showed moderate predictive value for stone presence, and their positive correlation with inflammatory markers such as CRP supports the notion that GDF-15 may reflect both local and systemic inflammatory responses associated with ureteral obstruction." (PMID 41515626, 2026). "Western blot analysis further confirmed that GDF15 and GFRAL expression levels progressively decreased with prolonged ureteral obstruction." (PMID 41474228, 2026).
acute lymphoblastic leukemia (4 papers, 2015 to 2023). Leukemia with an acute onset, characterized by the presence of lymphoblasts in the bone marrow and the peripheral blood. "Acute lymphoblastic leukemia (ALL) cells secrete pro-growth differentiation factor-15 (pro-GDF15) during chemotherapy, which can be cleaved by therapy-induced niche (TI-niche) cell-provided furin and subsequently activate TGF-β signaling to promote chemoresistance." (PMID 36593970, 2023).
aortic valve stenosis (4 papers, 2020 to 2025). Aortic valve stenosis (AVS) is a condition characterized by narrowing of the heart's aortic valve opening. "A Web Of Science search was performed with the following structure: (TS = ((“transcatheter aortic valve replacement” OR “tavi” OR “aortic valve stenosis/surgery” OR “aortic valve stenosis/therapy” OR “aortic valve replacement”))) AND TS = (LGALS3 OR GDF-15 OR galectin 3 OR galectin-3)." (PMID 41010905, 2025). "The GDF-15 test can be used in patients with reduced LV ejection fractions and suspected severe aortic valve stenosis when echocardiography parameters correspond to moderate stenosis and no additional investigations have been performed, such as stress echocardiography." (PMID 33477548, 2021).
brain cancer (4 papers, 2019 to 2023). A primary or metastatic malignant neoplasm affecting the brain. "For instance, in pancreatic as well as in brain cancer cells it was recently shown that tumor-dependent compressive cellular stress upregulates cell migration in a GDF15 manner." (PMID 34948405, 2021). "It should be also noted that in both cases, the migratory ability of both cell lines was inhibited, suggesting that MEK1/Erk1 activation and GDF15 expression can synergistically regulate brain cancer cell migration under mechanical compression." (PMID 31612114, 2019). "To this end, we set to examine whether GDF15 is also necessary for brain cancer cell migration under stress conditions by transiently transfect cells with siRNA against GDF15 (siGDF15)." (PMID 31612114, 2019). "Furthermore, Erk1 was found to be activated in compressed siGDF15-treated brain cancer cells, suggesting that GDF15 could act as a negative regulator of Erk1 activation in response to compression." (PMID 31612114, 2019). "However, our results showed that Erk1 is activated when GDF15 has been knockdown, suggesting a possible negative feedback loop between GDF15 and Erk1 activation in brain cancer cells under compression." (PMID 31612114, 2019).